HOXC6 (homeobox C6)
Description:
Sequence-specific transcription factor which is part of a developmental regulatory system that provides cells with specific positional identities on the anterior-posterior axis.
Synonyms: HOX3C; CP25; HHO.C8; HOX3
Tractability: PROTAC: ubiquitination databases record sites on it.
Gene: Protein-coding gene on chromosome 12 (53,990,624 to 54,030,823, forward strand). Ensembl gene ENSG00000197757.
Subcellular location: Nucleus
Subcellular location (Human Protein Atlas): Nucleoplasm; Cytosol
Gene Ontology:
Molecular function: DNA-binding transcription factor activity, RNA polymerase II-specific; RNA polymerase II cis-regulatory region sequence-specific DNA binding; DNA binding; DNA-binding transcription factor activity
Biological process: anterior/posterior pattern specification; regulation of transcription by RNA polymerase II; regulation of DNA-templated transcription
Cellular component: nucleoplasm; chromatin; nucleus
Genetic constraint (gnomAD): Loss-of-function variants: 10 observed, 25.32 expected, observed/expected ratio (o/e) 0.39, 90% interval 0.24 to 0.67. The upper end of that interval is the gene's LOEUF score, 0.67, which puts it in group 2 of 6, group 1 being the genes least tolerant of losing a copy. Missense variants: 258 observed, 326.86 expected, observed/expected ratio (o/e) 0.79, 90% interval 0.71 to 0.88. Synonymous variants: 123 observed, 138.32 expected, observed/expected ratio (o/e) 0.89, 90% interval 0.77 to 1.03.
Homologues: Orthologues: chimpanzee HOXC6 (100% identical), macaque HOXC6 (100% identical), mouse Hoxc6 (100% identical), rat Hoxc6 (100% identical), guinea pig HOXC6 (99% identical), pig HOXC6 (99% identical), rabbit HOXC6 (99% identical), tropical clawed frog hoxc6 (86% identical), zebrafish hoxc6b (73% identical), zebrafish hoxc6a (65% identical). Paralogues in human: HOXB6 (45% identical), HOXA6 (43% identical), HOXA7 (37% identical), HOXB7 (37% identical), HOXA5 (34% identical), HOXB5 (33% identical), HOXC8 (33% identical), HOXB8 (33% identical), HOXC4 (31% identical), HOXC5 (31% identical), HOXA4 (31% identical), HOXD8 (31% identical), and 30 more.
Diseases named in the same sentence as HOXC6 in open-access papers:
HOXC6 is named in the same sentence as 74 diseases in open-access papers, as found by Europe PMC text mining. Sharing a sentence is not in itself a finding about the gene and the disease. The quoted sentences say what the papers report.
prostate carcinoma (39 papers, 2011 to 2026). A carcinoma that arises from epithelial cells of the prostate gland. "SelectMDx is a test that combines clinical parameters (PSA, DRE, prostate volume, age and family history) with two urinary prostate cancer associated genes (HOXC6 and DLX1)." (PMID 32957584, 2020). "HOXC6, previously implicated in both breast and prostate cancer, has an important role in regulating cellular development, including differentiation, apoptosis, signalling and subsequent angiogenesis." (PMID 33158116, 2020). "HOXC6 is a candidate gene for early prostate cancer diagnosis, and upregulated HOXC6 has been associated with poor survival in gastric cancer patients." (PMID 27081081, 2016). "HOXC6 is involved in epithelial cell proliferation, and loss of this gene induces apoptosis in prostate cancer cells." (PMID 27833659, 2016). "Curiously, however, about half of the genes positively regulated by HOXC6 in experimental models are actually downregulated in prostate cancers, including three genes encoding inhibitors of WNT signaling, WIF1, DKK3 and SFRP1." (PMID 24213107, 2011). "HOXC6 RNA has been shown to be a potential diagnostic marker for prostate cancer as part of a multigene panel and has prognostic significance in gastric cancer, prostate cancer, breast cancer, and childhood acute lymphoblastic leukemia." (PMID 35432534, 2022). "An unbiased analysis of DNA methylation and gene expression data using a large set of tumors from TCGA identified HOXB13, HOXC4, HOXC5, and HOXC6 in the set of the top 10 transcription factors whose expression is linked to the creation of newly active distal regulatory elements in prostate cancers." (PMID 30866492, 2019). "A recent study has demonstrated that HOXC6 can exert diagnostic value in early detection and has monitoring function on progression or response to therapy, thus serving as a novel biomarker for prostatic cancer." (PMID 30559605, 2018). "As one of the 39 HOX genes in humans, HOXC6 is overexpressed in several cancers, including osteosarcoma, lung adenocarcinoma, and prostate cancer." (PMID 40255403, 2025). "This test measures the mRNA levels of three cancer-related genes: DLX1 (a prostate cancer cell proliferation gene), HOXC6 (a prostate cancer progression gene), and KLK3 (a prostate cancer reference gene)." (PMID 41374944, 2025). "HOXC6 mRNA was overexpressed in many cancers, especially in brain and CNS cancer, lung cancer, lymphoma and prostate cancer." (PMID 35488304, 2022). "The transcriptional network regulated by HOXC6 plays crucial roles in the proliferation, survival, and metastasis of prostate cancer cells." (PMID 35432534, 2022). "Recently, a large multicenter trial including 1955 patients prior to initial prostate biopsy compared performance of urinary HOXC6 and DLX1 mRNA (combined with other risk factors) with Prostate Cancer Prevention Trial Risk Calculator (PCPTRC)." (PMID 33922626, 2021). "Markers selected for the model include well-known genes associated with prostate cancer and proven in other diagnostic tests, such as PCA3, HOXC6, and the TMPRSS2/ERG gene fusion." (PMID 33925381, 2021). "To test if this is also true for the human HOX genes that are upregulated in prostate cancer, we compared the binding sites for HOXC6 and HOXC4." (PMID 32012197, 2020). "In summary, we have shown that HOXC4 and HOXC6 regulate critical genes affecting prostate cancer proliferation." (PMID 32012197, 2020). "It has also been revealed that HOXC6 can help in preventing apoptosis of prostate cancer cells by repressing the expression of neutral endopeptidase (NEP) and IGFBP-3." (PMID 32745141, 2020). "In prostate cancer, the upregulation of HOXC6 can not only participate in the process of PCa but also serves as an independent prognostic indicator of cancer." (PMID 32509568, 2020).
prostate carcinoma (continued). "Towards this goal, we identified genes that are affected by knockdown of HOXC4 and/or HOXC6 in 22Rv1 prostate cancer cells and performed ChIP-seq to characterize their genome-wide binding profiles." (PMID 32012197, 2020). "Binding sites for HOXC9 (in neuroblastoma cells) and HOXC6 (in prostate cancer cells) have been identified using an antibody to a tagged, exogenously expressed protein." (PMID 30866492, 2019). "Others have developed a 16-gene panel and a 5-gene panel of prostate cancer markers that include HOXC6; both panels can predict recurrence of prostate cancer after treatment." (PMID 30866492, 2019). "For instance, overexpressed HOXC6 is frequently observed in prostate cancers and relates to adverse clinical parameters." (PMID 30559605, 2018). "Here, we perform a computational prediction and identify a module of mutually exclusive transcriptional drivers, AR, HOXC6 and NKX2-2, which co-dysregulate a core set of metastasis-associated miRNAs in prostate cancer." (PMID 28397780, 2017). "The differentially expressed gene-list contained various genes previously reported to be differentially expressed in low- and intermediate/high-grade prostate cancer such as HOXC6, MAGEC2, HERPUD1 and SATB1." (PMID 27191985, 2016). "Overexpression of the classical homeobox transcription factor HOXC6 is frequent in prostate cancers and correlates with adverse clinical parameters." (PMID 24213107, 2011). "Accordingly, our data call for further detailed research on the HOXC6 paradox in prostate cancer which should yield important results for clinical application as well as insights into basic mechanisms of transcription." (PMID 24213107, 2011). "Here we report an expression analysis of HOXC6 and three of its target genes in a well-characterized series of prostate cancer tissues." (PMID 24213107, 2011). "Our data confirm the reported correlation of HOXC6 expression with clinical parameters of prostate cancer progression." (PMID 24213107, 2011). "We observed striking HOXC6 overexpression in our small, but well-characterized prostate cancer tissue series." (PMID 24213107, 2011). "Likewise, in prostate cancer, elevated levels of HoxC6 correlated with tumour proliferation, while knockdown of HoxC6 resulted in marked reduction in the proliferative index of prostate cancer cell lines." (PMID 41535654, 2026). "HOXC6 is used in the SelectMDx prostate cancer urine test alongside DLX1." (PMID 36765747, 2023). "In recent years, an increasing number of studies have confirmed that HOXC6 is involved in many physiological and pathophysiological processes, such as those in nasopharyngeal carcinoma, gastric cancer, oesophageal squamous cell carcinoma, and prostate cancer." (PMID 35488304, 2022). "In addition, we showed colocalization of HOXC4 and HOXC6 at HOXB13 sites that are also bound by FOXA1 and AR, which have been previously linked to regulation of prostate cancer cell proliferation." (PMID 32012197, 2020). "In support of this hypothesis, studies have shown that targeted reduction in levels of HOXC6 can increase apoptosis while reducing proliferation of prostate cancer cells." (PMID 32012197, 2020). "A better understanding of the molecular function of HOXC4 and HOXC6 could provide a more comprehensive understanding of prostate cancer." (PMID 32012197, 2020). "To begin to address the role of HOXC4 and HOXC6 in prostate cancer, we performed RNA-seq analyses before and after siRNA-mediated knockdown of HOXC4 and/or HOXC6 and also performed ChIP-seq to identify genomic binding sites for both of these transcription factors." (PMID 32012197, 2020). "Some studies that have been published on HOXC6 so far, particularly in prostate cancer." (PMID 32745141, 2020). "HOXC6, a member of the homeobox family that encodes highly conserved transcription factors, not only plays a crucial role in CRC, but also functions as an independent prognostic marker for hepatocellular carcinoma and prostate cancer." (PMID 31689990, 2019).
prostate carcinoma (continued). "HOXC6 gene silencing enables prostate cancer cell to apoptosis." (PMID 30559605, 2018). "Unfortunately, examining H3K27ac ChIP-seq data in multiple prostate cancer cell lines suggested that AR, HOXC6 and NKX2-2 are not broadly associated with super enhancers." (PMID 28397780, 2017). "Next, We examined whether the observed mutual exclusivity between AR, HOXC6 and NKX2-2 overexpression is specifically associated with prostate cancer, or represents an intrinsic property of tumorigenesis." (PMID 28397780, 2017). "We showed that HOXC6 and DLX1 are associated with different clusters of prostate tumor-specific enhancers and confer distinct transcriptomic changes upon knockdown in C42B prostate cancer cells." (PMID 27833659, 2016). "Since surprisingly many HOXC6 target genes are downregulated in prostate cancer, it has been posited that oncogenic effects of HOXC6 in prostate cancer may be unmasked by concurrent epigenetic downregulation of target genes exerting tumor suppressive effects." (PMID 24213107, 2011). "Our data support the hypothesis that HOXC6 target genes exerting tumor-suppressive effects are epigenetically downregulated in prostate cancer, but DNA methylation appears to follow or bolster rather than to cause their transcriptional inactivation." (PMID 24213107, 2011). "These target genes are upregulated by HOXC6 and could plausibly mediate its effects on prostate cancer progression and metastasis." (PMID 24213107, 2011). "According to this hypothesis, HOXC6 can activate both target genes promoting and preventing prostate cancer progression, but epigenetic inactivation of its tumor-suppressive targets would restrict its effect to cancer-promoting genes." (PMID 24213107, 2011). "In order to explain our findings, we would like to propose the idea that the changed composition of transcription factors (and cofactors) in the nuclear milieu of prostate cancer cells may lead to a switch of HOXC6 function at some of its target genes." (PMID 24213107, 2011). "Thus, HOXC4 and HOXC6 are clinically relevant biomarkers of aggressive prostate cancer." (PMID 32012197, 2020). "In prostate cancer (PCa), METTL3 induces homeobox C6 (HOXC6) m6A modification to stabilize its expression and promote cancer cell proliferation, invasion, migration, stemness, and glycolysis." (PMID 41256854, 2025). "The SelectMDx (MDxHealth, Irvine, CA, USA) assay measures the mRNA levels of two genes, HOXC6 and DLX1, that are known to be overexpressed in aggressive prostate cancer." (PMID 36768533, 2023). "HOXC6 and HOXC4 have been previously identified as promising, easy to assay (urinary-based) biomarkers of aggressive prostate cancer that can enhance early diagnosis and predict cancer recurrence after treatment." (PMID 32012197, 2020). "Our studies demonstrate that HOXC4 and HOXC6 co-localize with HOXB13, FOXA1 and AR, three transcription factors previously shown to contribute to the development of prostate cancer." (PMID 32012197, 2020). "Thus, increased levels of HOXC6 in prostate cancer may promote tumorigenesis either by enhancing overall protein levels (which would enable accelerated cell proliferation) or by supporting prostate cancer metastasis to the bone environment." (PMID 32012197, 2020). "For example, HOXC6 and DLX1 genes, which are biomarkers and key players of prostate cancer development as well as genes involved cell cycle (CDK4, CDC23, MYC) and androgen signaling (AR, GRHL2) are found." (PMID 31515496, 2019). "This supports the recent finding that the combination of three genes (HOXC6, DLX1, and TDRD1) constitutes the top prognostic marker for prostate cancer." (PMID 27833659, 2016). "Several other genes in the top 10 upregulated probesets are also overexpressed in tumours including PCP4 in leiomyomas, HOXC6 in oesophageal, breast and lung carcinomas and IL16RA2 in glioblastomas, prostate cancer and adrenocortical tumours." (PMID 24148222, 2013).
prostate carcinoma (continued). "For example, HOXC6, a homeobox transcription factor, regulates the expression of genes including BMP7, FGFR2, IGFP3 and PDGFRA to influence oncogenic activities in prostate cancer." (PMID 24009521, 2013). "The function of HOXC6 in PDAC is not clear, but high expression of HOXC6 in prostate cancer was correlated with disease development." (PMID 34095461, 2021). "Aberrant expression of HOXC6 and HOXC4 is commonly detected in prostate cancer." (PMID 32012197, 2020). "Specifically, it is not clear if HOXC4, HOXC5, and HOXC6 are all drivers of prostate cancer or if the three proteins are all upregulated due to genomic proximity, but only one is a direct regulator of tumorigenesis." (PMID 30866492, 2019). "For example, HOXC6 directly regulates gene expression of Bone morphogenetic protein 7 (BMP7), Fibroblast growth factor receptor 2 (FGF2), and Platelet-derived growth factor receptor (PDGFR) in prostate cancer." (PMID 30993034, 2019). "However, knocking down LSD1 did not upregulate metastasis-associated miRNAs in either LnCAP cells or in RWPE-1 cells overexpressing AR, HOXC6 or NKX2-2, suggesting that other co-factors mediate the transcriptional repression of miRNAs in prostate cancer." (PMID 28397780, 2017). "However, different genes were identified upon knockdown of HOXC6 and DLX1, suggesting that each of these TFs has a distinct role in prostate cancer." (PMID 27833659, 2016). "Interestingly, HOXC6 and DLX1 were recently identified as top markers for prostate cancer, but little is known about their target genes." (PMID 27833659, 2016). "Interestingly, several well-known genes, despite being recommended for their utility in the identification of patients at risk of prostate cancer at RNA expression level, are by far not in the top of this list (e.g. in urine; PCA3, HOXC6, DLX1)." (PMID 31170942, 2019). "Some of these genes were already extensively studied in prostate cancer, mostly those upregulated in tumor tissue: SPINK1 (Top17, logFC 4.8), ETV4 (Top63, logFC 3.6), PCA3 (Top79, logFC 3.5), TDRD1 (Top86, logFC 3.4), AMACR (Top105, logFC 3.2), DLX1 (Top110, logFC 3.1), HOXC6 (Top268, logFC 2.3)." (PMID 31170942, 2019). "Recent evidence suggests that homeobox C6 (HOXC6) gene, a critical player in milk production and mammary gland development, has been found to be overexpressed in medulloblastomas and osteosarcomas, as well as in variety of carcinomas including breast, lung and prostate cancer s." (PMID 30559605, 2018). "The lack of synergy among AR, HOXC6 and NKX2-2 suggests that the three master TFs may indeed compete for a common epigenetic co-factor to inhibit miRNA expression in prostate cancer." (PMID 28397780, 2017).
gastric cancer (16 papers, 2016 to 2024). A primary or metastatic malignant neoplasm involving the stomach. "Overexpressed HOXC6 is closely linked to poor survival of patients with gastric cancer, and contributes to gastric carcinogenesis progression." (PMID 30559605, 2018). "Additionally, HOXC6/8/9/10/11/13 are overexpressed in gastric cancer (GC) and are associated with an unfavorable prognosis." (PMID 38311789, 2024). "Homeobox C6 (HOXC6) is a transcription factor that is implicated in the malignant progression of several cancers, including gastric cancer, hepatocellular carcinoma, colon carcinoma." (PMID 36176299, 2022). "The expression levels of HOXC6 mRNA in patients with advanced gastric cancer (AGC) were significantly higher than those in patients with early gastric cancer (EGC)." (PMID 32745141, 2020). "The increased expression of HOXC6 in gastric cancer cell lines significantly activated extracellular signals regulating kinase signal transduction and MMP9 upregulation, which promoted the migration and invasion of gastric cancer cells." (PMID 32509568, 2020). "HOXC6 promotes the migration, invasion, and progression of gastric cancer by upregulating Matrix metalloproteinase 9 (MMP9)." (PMID 30993034, 2019). "HOXC6 overexpression promoted cell migration, invasion and proliferation, where decreased HOXC6 expression reversed the facilitation effect on gastric cancer cells." (PMID 30886783, 2019). "It has revealed that HOXC6 overexpression induced colony formation and cell proliferation in gastric cancer." (PMID 30559605, 2018). "In gastric cancer, the upregulation of HOXC6 can increase the migration and invasion ability of gastric cancer cells, while the interference of HOXC6 expression can inhibit the migration and invasion of gastric cancer cells." (PMID 32509568, 2020). "Examples include HOXC6 in gastric cancer, HOXB8 in ovarian cancer, and HOXD3 in breast cancer." (PMID 26867567, 2016). "HOXC6, as an important transcription factor, enhances the MMP-9 activity and is involved in increasing the metastasis of gastric cancer." (PMID 34054953, 2021). "For example, the HOXB gene is a prognostic factor in breast cancer 14, HOXA13 expression impaired the chemotherapy in gastric cancer cells 15, HOXB5 promotes metastasis in hepatocellular carcinoma 16 and HOXA13, HOXD13, and HOXC6 were promoted colorectal cancer 17-19." (PMID 37670969, 2023).